RAD50 (RAD50 double strand break repair protein)
Description:
Component of the MRN complex, which plays a central role in double-strand break (DSB) repair, DNA recombination, maintenance of telomere integrity and meiosis. The MRN complex is involved in the repair of DNA double-strand breaks (DSBs) via homologous recombination (HR), an error-free mechanism which primarily occurs during S and G2 phases. The complex (1) mediates the end resection of damaged DNA, which generates proper single-stranded DNA, a key initial steps in HR, and is (2) required for the recruitment of other repair factors and efficient activation of ATM and ATR upon DNA damage. The MRN complex possesses single-strand endonuclease activity and double-strand-specific 3'-5' exonuclease activity, which are provided by MRE11, to initiate end resection, which is required for single-strand invasion and recombination. Within the complex, RAD50 is both required to bind DNA ends and hold them in close proximity and regulate the activity of MRE11. RAD50 provides an ATP-dependent control of MRE11 by positioning DNA ends into the MRE11 active site: ATP-binding induces a large structural change from an open form with accessible MRE11 nuclease sites into a closed form (By similarity). The MRN complex is also required for DNA damage signaling via activation of the ATM and ATR kinases: the nuclease activity of MRE11 is not required to activate ATM and ATR. The MRN complex is also required for the processing of R-loops. In telomeres the MRN complex may modulate t-loop formation.
Synonyms: hRAD50; RAD50-2; NBSLD; RAD502
Tractability: PROTAC: ubiquitination databases record sites on it; its protein half-life has been measured.
Target class: Enzyme; Hydrolase
Gene: Protein-coding gene on chromosome 5 (132,556,019 to 132,646,349, forward strand). Ensembl gene ENSG00000113522.
Subcellular location: Nucleus; Chromosome, telomere; Chromosome
Subcellular location (Human Protein Atlas): Nucleoplasm; Nuclear bodies
Pathways (Reactome):
DNA Repair: HDR through Homologous Recombination (HRR); HDR through MMEJ (alt-NHEJ); HDR through Single Strand Annealing (SSA); Homologous DNA Pairing and Strand Exchange; Nonhomologous End-Joining (NHEJ); Presynaptic phase of homologous DNA pairing and strand exchange; Processing of DNA double-strand break ends; Recruitment and ATM-mediated phosphorylation of repair and signaling proteins at DNA double strand breaks; Resolution of D-loop Structures through Holliday Junction Intermediates; Resolution of D-loop Structures through Synthesis-Dependent Strand Annealing (SDSA); Sensing of DNA Double Strand Breaks
Disease: Defective HDR through Homologous Recombination Repair (HRR) due to PALB2 loss of BRCA1 binding function; Defective HDR through Homologous Recombination Repair (HRR) due to PALB2 loss of BRCA2/RAD51/RAD51C binding function; Defective homologous recombination repair (HRR) due to BRCA1 loss of function; Impaired BRCA2 binding to PALB2; Impaired BRCA2 binding to RAD51
Cell Cycle: G2/M DNA damage checkpoint
Cellular responses to stimuli: DNA Damage/Telomere Stress Induced Senescence
Developmental Biology: Differentiation of naive CD4+ T cells to T helper 2 cells (Th2 cells)
Reproduction: Meiotic recombination
Gene Ontology:
Molecular function: 3'-5' exonuclease activity; ATP hydrolysis activity; DNA binding; DNA helicase activity; identical protein binding; protein binding; protein serine/threonine kinase activator activity; protein-macromolecule adaptor activity; single-stranded DNA endodeoxyribonuclease activity; double-stranded telomeric DNA binding; G-quadruplex DNA binding; single-stranded telomeric DNA binding
Biological process: DNA damage response; DNA double-strand break processing; DNA recombination; DNA repair; DNA strand resection involved in replication fork processing; double-strand break repair; double-strand break repair via homologous recombination; negative regulation of telomere capping; positive regulation of double-strand break repair; positive regulation of telomere maintenance; R-loop processing; regulation of mitotic recombination; telomere maintenance via telomerase; telomeric 3' overhang formation; chromosome organization involved in meiotic cell cycle; homologous recombination; mitotic G2/M transition checkpoint; reciprocal meiotic recombination; telomere maintenance; telomere maintenance via recombination; chromosome organization
Cellular component: BRCA1-C complex; chromosome; chromosome, telomeric region; membrane; Mre11 complex; nuclear body; nucleoplasm; nucleus; site of double-strand break; chromosomal region; condensed nuclear chromosome
Genetic constraint (gnomAD): Loss-of-function variants: 130 observed, 169.08 expected, observed/expected ratio (o/e) 0.77, 90% interval 0.67 to 0.89. The upper end of that interval is the gene's LOEUF score, 0.89, which puts it in group 3 of 6, group 1 being the genes least tolerant of losing a copy. Missense variants: 1,345 observed, 1,595.7 expected, observed/expected ratio (o/e) 0.84, 90% interval 0.81 to 0.88. Synonymous variants: 525 observed, 522.51 expected, observed/expected ratio (o/e) 1, 90% interval 0.94 to 1.08.
Gene-disease validity (ClinGen):
ClinGen rates the evidence that RAD50 causes each of these diseases.
familial ovarian cancer (autosomal dominant): Refuted. An instance of ovarian cancer that is caused by an inherited modification of the individual's genome.
hereditary breast carcinoma (autosomal dominant): Refuted. Breast carcinoma that has developed in relatives of patients with history of breast carcinoma.
Cancer hallmarks: proliferative signalling (promotes); genome instability and mutations (suppresses); invasion and metastasis (promotes); invasion and metastasis (suppresses); cell replicative immortality (promotes); escaping programmed cell death (promotes); escaping programmed cell death (suppresses); angiogenesis (suppresses)
Homologues: Orthologues: chimpanzee RAD50 (99% identical), dog RAD50 (96% identical), macaque RAD50 (96% identical), rabbit RAD50 (93% identical), mouse Rad50 (92% identical), rat Rad50 (92% identical), pig RAD50 (92% identical), guinea pig RAD50 (90% identical), tropical clawed frog rad50 (76% identical), zebrafish rad50 (71% identical), Drosophila melanogaster rad50 (28% identical), Caenorhabditis elegans rad-50 (25% identical).
Diseases named in the same sentence as RAD50 in open-access papers:
RAD50 is named in the same sentence as 145 diseases in open-access papers, as found by Europe PMC text mining. Sharing a sentence is not in itself a finding about the gene and the disease. The quoted sentences say what the papers report.
breast cancer (98 papers, 2008 to 2025). A primary or metastatic malignant neoplasm involving the breast. "Taken together, we describe RAD50 missense variants, previously identified in breast cancer patients, that support mitotic progression and DNA damage response toward TopoII poisoning to varying extents." (PMID 41031707, 2025). "Since epirubicin is the standard drug in breast cancer treatment and evoked this characteristic difference in RAD50‐deficient cells, we chose epirubicin response as a readout to further monitor RAD50 function." (PMID 41031707, 2025). "For analyzing the impact of different RAD50 variants on specific RAD50 functions, we selected six RAD50 missense variants that had been associated with breast cancer in an early study." (PMID 41031707, 2025). "This indicates that GNPDA1 is linked to several genes such as BRCA1 and RAD50 and is associated with DNA damage and breast cancer." (PMID 40278313, 2025). "RAD50 gene was associated with intermediate risk of developing breast cancer and updating the classification of this variant is important for better disease risk management." (PMID 38313678, 2024). "Analyses of the RAD50 gene have shown that its germline variants are associated with colorectal, pancreatic, hepatocellular or breast cancer risk." (PMID 36982687, 2023). "The absence of zinc hook LOF germline mutations RAD50Q672X and RAD50K722fs in another large RAD50 breast cancer study in 7657 Chinese patients further demonstrated their potential genetic predisposition role in familial ESCC." (PMID 34572942, 2021). "RAD50 haploinsufficiency observed in T-lymphocytes of Finnish breast cancer patients carrying heterozygous LOF mutations such as the Finnish founder mutation RAD50 687delT resulted in increased genomic instability." (PMID 34572942, 2021). "The genetic predisposition role of RAD50 in inherited breast cancer has been documented, while its role in breast cancer is still controversial." (PMID 34572942, 2021). "Mutations of the adjacent and conserved Rad50 D-loop leucine and aspartate residues have been found in solid metastatic and breast cancer cells, respectively." (PMID 31889185, 2020). "Accumulating evidence indicates that RAD50 is a breast cancer susceptibility gene associated with genomic instability." (PMID 33240314, 2020). "They detected significant associations of some haplotypes of BABAM1, ATM, CTIP (RBBP8), TOPBP1, BRIP1, BRE and RAD50 with the modification of breast cancer risk." (PMID 30823486, 2019). "Multi-gene panel testing revealed no mutations in the mismatch repair, BRCA1/2, or PTEN genes but a deleterious frameshift mutation in RAD50, a moderate penetrance breast cancer gene." (PMID 30093976, 2018). "Nevertheless, other studies have indicated that mutations in RAD51C and RAD51D contribute to the risk of both breast and ovarian cancer, and that RAD50 is an intermediate-risk breast cancer susceptibility gene." (PMID 29566657, 2018). "Two patients with the deleterious mutation BRCA2 or RAD50 had male family members with breast cancer." (PMID 26824983, 2016). "RAD51 (RAD50 forms MRE11-NSB1-RAD50 complex) also interacts with breast cancer susceptibility genes 1 and 2 (BRCA1/BRCA2)." (PMID 24752797, 2014). "Although, the germline c.687delT mutation in RAD50 has been linked to sporadic breast cancer in the Finnish population, our results excluded the mutation as a risk variant in Polish breast cancer patients." (PMID 24093751, 2013). "Many reports described the contribution of the RAD50 gene variants to breast cancer susceptibility in various populations." (PMID 24093751, 2013). "The c.687delT RAD50 mutation was reported with significantly elevated frequency in breast cancer patients from Finland." (PMID 24079363, 2013). "Mutations in ATM, BRIP1, PALB2, CHEK2 and possibly NBS1, RAD50 are also associated with a moderately increased risk for breast cancer, and many low penetrance genes have recently been identified." (PMID 18706089, 2008).
breast cancer (continued). "Therefore, RAD50 as well as MRE11 (encoding its binding partner) have been proposed as prognosis‐significant DNA repair genes to establish prediction models in breast cancer patients." (PMID 41031707, 2025). "In particular, breast cancer risk does not seem to be generally increased by truncating or missense RAD50 variants, although certain substitutions such as the Finnish founder variant RAD50*c.687delT may confer some increased breast cancer risk." (PMID 41031707, 2025). "Among the 10 breast cancer susceptibility genes, 10.3% (13/126) of patients harbored pathogenic germline variations, whereas one patient was observed to possess pathogenic variations in both RAD50 and BRCA1." (PMID 39482530, 2024). "These earlier contradictory observations support the notion that rare deleterious missense or LOF mutations in key functional domains of RAD50 may associate with breast cancer in an ethnicity specific or early-onset manner." (PMID 34572942, 2021). "The RAD50 pathogenic mutations in breast cancer such as the Finnish founder mutation RAD50 687delT may be population specific." (PMID 34572942, 2021). "Mutation in RAD50 is associated with breast cancer, genome instability and poor survival." (PMID 33194615, 2020). "A correlation between germline mutations of RAD50 and breast cancer risk is still unclear." (PMID 32668560, 2020). "RAD50 is a breast cancer susceptibility gene associated with genomic instability." (PMID 31872854, 2020). "By this approach, we identified loss‐of‐function mutations in 6/20 (30%) probands, five of which occurred on BRCA1, CHEK2, and ATM and are esteemed to be risk‐relevant according to our studies, while a novel RAD50 truncating mutation is most likely unrelated to breast cancer." (PMID 29271107, 2018). "In contrast, a novel RAD50 truncating mutation is most likely unrelated to breast cancer." (PMID 29271107, 2018). "Extended mutation screening for RAD50 R385C using allele-specific real-time polymerase chain reaction (PCR) methodology excluded this rare variant in an additional 163 unrelated breast cancer patients stratified according to ER status (49 ER-negative, 114 ER-positive)." (PMID 28241424, 2017). "Similarly, biallelic mutations in RAD50 give rise to a NBS-like disorder whereas heterozygotes for a Finnish founder mutation are predisposed towards breast cancer." (PMID 24025454, 2013). "Heterozygous RAD50 mutational status may be associated with breast cancer risk in the Finnish population but large case–control studies have not confirmed an overall association of RAD50 germline variants with breast cancer risk." (PMID 41031707, 2025). "To further identify the synergies between INPP4B and RAD50 on clinical consequences at the genetic level, we are motivated to identify the relevant disease-associating SNPs that affect the expression of each gene and are collectively prognostic of the clinical outcome of breast cancer patients." (PMID 31872854, 2020). "The role of RAD50 in inherited breast cancer is well known, and some authors have demonstrated that the overexpression of RAD50 in TNBC cells allows them to recover better from chemotherapeutic drugs through the MRN complex." (PMID 40282418, 2025). "While TCGA has revolutionized cancer biomarker discovery, exemplified by studies identifying SCN3B in glioma, CDK2 in glioma prognosis, AIMP1/CNIH4 in head-neck squamous carcinoma, and RAD50 in breast cancer, its limitations must be acknowledged." (PMID 40860678, 2025). "Among participants with family history of breast cancer, PTVs in ATM (p-value = 0.002), BRCA2 (p-value = 0.005), BRCA1 (p-value = 0.046), PALB2 (p-value = 0.039) and RAD50 (p-value = 0.044) were significantly associated with increased risk of breast cancer." (PMID 37790698, 2023). "Among participants with a family history of breast cancer, PTVs in ATM, BRCA2, BRCA1, PALB2 and RAD50 were associated with an increased risk of breast cancer." (PMID 37790698, 2023).
breast cancer (continued). "In Western blots, RAD50 was overexpressed in breast cancer cells (MCF7, AU565, and BT474) compared with normal breast epithelial cells (MCF10A)." (PMID 37445737, 2023). "The hazard ratio of other six genes (FAAP20, RRM2B, UBE2A,RAD50,MRE11, and RPA3) was >1, regarded as risk factors in developing breast cancer." (PMID 36713553, 2022). "In another study of MRN expression in breast cancers, the authors reported reduced RAD50 (3%), MRE11 (7%) and NBS1 (10%) protein expression, particularly in triple-negative disease, high-grade tumours and in familial breast cancers." (PMID 34782604, 2021). "We have previously demonstrated that INPP4B and RAD50 collectively affect breast cancer survival at the transcriptional and translational levels." (PMID 31872854, 2020). "We found a significant positive association of HERV expression with RAD50 and with AC060780.1, which suggest a possible role of HERV in regulating breast cancer genes from PLWH with breast cancer." (PMID 33194615, 2020). "Reported DSB repair variants in breast cancer comprise PALB2, NBN, RAD51, ATM, CHEK2, ATR, RAD50, and WRN." (PMID 31658756, 2019). "Here, RAD50 predicts poor survival in only five cancer types, prostate, adrenocortical, breast cancer, low-grade glioma, and head and neck cancers." (PMID 30345029, 2018). "Here we see the RAD50 is one of the most significant predictors of poor overall survival in basal-like breast cancer." (PMID 30345029, 2018). "Here we can see that the DNA repair protein, RAD50 is a poor prognostic marker for overall and disease-specific survival in basal-like breast cancer." (PMID 30345029, 2018). "Mre11, Rad50, and Nbs1 form MRN complex, which facilitate DNA repair and also reported that NBN gene encoding Nbs1, has the strong association with breast cancer." (PMID 28477017, 2017). "An intact MRN complex predicts a good response to treatment in patients with early breast cancer, whereas mutations in MRE11, NBS1, or RAD50 have been linked to increased risk of cancer, including sporadic and familial cancers." (PMID 29189711, 2017). "In some breast cancer patients, loss of RAD17, RAD50, and RAP80 s genes which participate into the BRCA1‐dependent DNA repair was associated with significantly increased genomic instability and poor patient survival." (PMID 26663100, 2016). "Lowered expression of Rad50 and Mre11, both of which are key components of the MRN complex and linked to increased breast cancer susceptibility, was also identified." (PMID 27014724, 2016). "In the present work, we evaluated the contribution of rare variants in the genes MRE11A, RAD50, and NBN to breast cancer risk." (PMID 24894818, 2014). "Results reported here establish that MRE11A, RAD50, and NBN are intermediate-risk breast cancer susceptibility genes and help to justify their inclusion on panel-based cancer susceptibility gene tests." (PMID 24894818, 2014). "al has excluded any association of the RAD50/MRE11 polymorphisms and breast cancer risk, beside one SNP in NBN." (PMID 24079363, 2013). "Finally, a splicing mutation predicted to lead to exon skipping was identified in RAD50 gene in a breast cancer patient aged 37 years." (PMID 38313678, 2024). "Besides, rare variants in other genes like ATM, CHEK2, CDH1, PALB2, RAD50, and RAD51C have been detected mainly in the breast cancer subgroup." (PMID 39148954, 2024). "Together, the data imply that RAD50 status may aid prognostic stratification of patients in various cancers including sporadic breast cancers." (PMID 34782604, 2021).